BRAF (B-Raf proto-oncogene, serine/threonine kinase)
Diseases named in the same sentence as BRAF in open-access papers (continued):
Sharing a sentence is not in itself a finding about the gene and the disease.
melanoma (continued). "The most common BRAF mutation in melanoma (90% of cases with BRAF mutations) involves a glutamic acid substitution for valine 600 (V600E)." (PMID 32046325, 2020). "The constitutive activation of BRAF kinase is not only a driver mutation in melanoma, but also has effects on melanoma microenvironment composition." (PMID 33193402, 2020). "The impact of somatic alternations on immune responses has previously been shown in BRAF mutations in melanoma and IDH mutations in glioma." (PMID 32070062, 2020). "A combination of ICI with BRAFi and MEKi in BRAF-mutated melanomas was then developed in phase 1 studies." (PMID 32585901, 2020). "The serine/threonine protein kinase BRAF, physiologically involved in the control of cellular growth, is mutated in about 50% of all melanomas." (PMID 33036192, 2020). "The detection and quantitation of the mutated BRAF V600E protein in melanoma tissue by histopathological methods has some disadvantages." (PMID 32213878, 2020). "The majority of melanomas harbor mutations in either BRAF or RAS or NF1 that result in hyperactivation of the RAS/RAF/MEK/ERK (hereafter MAPK) signaling pathway." (PMID 32466509, 2020). "On the basis of the latest evidence, the combination of BRAFi and MEKi results in a better therapeutic response of melanoma patients positive to BRAF mutations." (PMID 32392801, 2020). "Chronic sun‐damaged (CSD) melanoma represents 10%–20% of cutaneous melanomas and is characterized by infrequent BRAF V600E mutations and high mutational load." (PMID 31811783, 2020). "Perhaps, the most remarkable progress has been made after the identification of BRAF mutations in melanoma." (PMID 32393282, 2020). "As an example, the identification of BRAF V600E mutation is important to indicate which melanoma patients will likely respond effectively to vemurafenib treatment." (PMID 32393282, 2020). "It has been found to activate the MAPK pathway by activating mutations of either NRAS or BRAF in most melanomas." (PMID 32556513, 2020). "Vemurafenib was specifically approved for melanomas with BRAF V600E-activating mutation, this agent inhibits the kinase activity that is responsible for hyperactivating the MAPK pathway." (PMID 33256089, 2020). "A mutation of BRAF in the RAS–RAF–MEK–ERK–MAP kinase pathway can be found in 66% of malignant melanomas." (PMID 32824576, 2020). "While several options are available for the treatment of BRAF-driven melanoma, limited targeted therapies are available for NRAS-mutated tumors, given the difficulties in directly targeting the Ras GTPase." (PMID 32517051, 2020). "In this review we will retrace the development of molecular-target drugs and the current therapeutic scenario for patients with BRAF mutated melanoma, from the introduction of BRAF inhibitors as single agents in 2011 to modern clinical practice." (PMID 32760738, 2020). "BRAF mutations and copy number variation have been widely investigated in melanoma, thyroid carcinoma, and lung and colon cancers." (PMID 33489866, 2020). "In this review, we will report the most commonly used BRAF diagnostic strategies for melanoma and the emerging techniques in the liquid biopsy field." (PMID 32695793, 2020). "This mutation is known as BRAF V600E mutation, and has been found in 100% of hairy cell leukaemias, in approximately 50% of melanomas, in 50% of papillary thyroid cancers or in 1–3% of non-small cell lung carcinomas." (PMID 31952366, 2020). "Both A375 and RPMI7951 melanoma cells bear the BRAF mutation (p.V600E) and CDKN2A mutation, however, only A375 cells harbor a homozygous mutation in the BRAF gene." (PMID 33114713, 2020).
melanoma (continued). "Nine of these patients had driver mutation data derived from the tumor specimen: 5/9 patients had BRAF/NRAS/KIT wild type melanoma, whereas 4/9 patients had BRAF or NRAS driver mutations identified in the tumor." (PMID 32785074, 2020). "In particular, the combination of inhibitors of oncogenic BRAFV600 mutants (BRAFi) and MEK inhibitors (MEKi) achieves significant clinical responses in patients with BRAF-mutated melanoma." (PMID 32466585, 2020). "The BRAF gene is commonly mutated in melanoma resulting in a constitutive function of the B-Raf protein." (PMID 32656079, 2020). "For instance, somatic mutations in CDKN2A and BRAF are commonly found in the sporadic form of melanoma." (PMID 32169117, 2020). "Targeted therapy interferes with mutation of the BRAF gene, which stimulates cells to develop abnormally and divide out of control, but the mutation occurs in around half of all melanoma." (PMID 32859054, 2020). "For example, the BRAF V600E mutation inhibits the activation of the Wnt/β-catenin pathway, promoting the apoptosis of melanoma cells." (PMID 31733641, 2020). "ctDNA was less frequently detected in NRAS-mutated than in BRAF-mutated melanoma (36% and 66%, respectively)." (PMID 32664549, 2020). "For example, BRAF V600E inhibitors have greatly improved survival outcomes in melanoma patients with said mutation." (PMID 33205077, 2020). "The activity of Vemurafenib, was evaluated in 146 patients with BRAF V600 mutated melanoma with brain metastases." (PMID 32575838, 2020). "In 2017 the results of the COMBI-MB, a phase 2 clinical trial designed to assess the safety and efficacy of Dabrafenib combined with Trametinib in patients with BRAF V600 mutated melanoma with brain metastases, were published." (PMID 32575838, 2020). "Identification of BRAF activating mutation as a key oncogene in approximately half of all melanomas has dramatically changed the current treatment strategy for metastatic melanoma." (PMID 32313236, 2020). "In ~50% of melanoma, urothelial, and thyroid cancers, TERTp mutations coexist with the common BRAF-V600E mutation." (PMID 32204305, 2020). "Some works reported that mutations in these genes sporadically arise in melanoma and cause a growth advantage to melanoma cell lines bearing BRAF mutations." (PMID 32528879, 2020). "Recently, a report has shown phosphorylation of S6 to be marker of sensitivity to BRAF mutated melanoma and that suppression of S6 after MAPK treatment was a predictor of progression-free survival." (PMID 32085796, 2020). "SCH772984 has shown promising results in a panel of melanoma cell lines, including cells with innate or acquired resistance to vemurafenib, cells with BRAF/NRAS double mutations or NRAS mutations (NCT02457793)." (PMID 32760738, 2020). "Two diagnoses were changed to CCS based on positive molecular findings, while in the remaining five cases mutational analysis for BRAF was performed, with confirmation as melanoma in three where the mutation was detected." (PMID 33061792, 2020). "Melanoma cells addicted to mutated BRAF oncogene activity can be targeted by specific kinase inhibitors until they develop resistance to therapy." (PMID 32784465, 2020). "Vemurafenib is a tyrosine kinase inhibitor and is a selective oral inhibitor of the oncogenic BRAF V600 kinase; this drug is approved for the treatment of melanoma patients harbouring this mutation." (PMID 33375286, 2020). "The efficiency of BRAF inhibitors in BRAF-V600E-mutated melanoma prompted the development of a similar approach in CRC." (PMID 32296018, 2020). "About 40–50% of melanoma patients have mutations in valine at position 600 (Val600) of BRAF protein, which leads to aberrant activation of MAPK pathway." (PMID 31820036, 2020). "An initial phase I trial tested the combination of ipilimumab and vemurafenib in patients with metastatic BRAF-mutated melanoma, but it was stopped early because of excessive toxicity." (PMID 33574893, 2020).
melanoma (continued). "Mutations in RAC1 are found in 4–9% of patients and is the third “hotspot” mutation in melanoma, following BRAF and NRAS." (PMID 32092958, 2020). "BRAF mutation has been assumed to be an early evolutionary event in tumor maturation, and play a central role in melanoma pathogenesis." (PMID 32313236, 2020). "Metastatic melanoma tumors with BRAF V600E mutations have a complete (6%) or partial tumor regression (62.5%) in most patients treated with the BRAF inhibitor." (PMID 31748891, 2020). "Large-scale sequencing efforts have led to the classification of melanoma into four major subtypes (i.e., BRAF-mutant, NRAS-mutant, NF1-deficient, and triple wild-type)." (PMID 33024276, 2020). "There are multiple trials investigating the IT-TT combination treatment for BRAF-mutated melanoma patients showing overall response rates of up to 100%, albeit with 22% of patients discontinuing treatment due to toxicity (COMBI-I trial)." (PMID 32487100, 2020). "The most prevalent class I BRAF mutations, V600D/E/K/R, frequent especially in melanoma and thyroid or colorectal cancers enable BRAF functioning as RAS-independent monomers." (PMID 32545208, 2020). "Melanoma cells are often characterized by an activated extracellular signal–regulated kinase (ERK) pathway induced by BRAF activating mutations." (PMID 32373541, 2020). "The BRAFV600E is a driver mutation in melanomas because it constitutively activates BRAF and the ERK pathway." (PMID 32283832, 2020). "On the other hand, BRAF mutations were found more common in melanomas with advanced stages like vertical growth phase, lymph node metastasis, or ulceration, suggesting that BRAF mutations correlated more with melanoma progression." (PMID 32083130, 2020). "BRAF is mutated in around 50% of melanomas, and some years ago, the therapeutic landscape of this tumor broadened through the development of BRAF inhibitors, specifically vemurafenib and dabrafenib." (PMID 32331425, 2020). "In our previous study, we investigated the prevalence of the BRAF V600 mutation among Indonesian melanoma cases using real-time polymerase chain reaction (RT-PCR) as the detection method and obtained a low percentage compared to Asia and other countries." (PMID 32188503, 2020). "Many studies have shown increased T cells in BRAF-mutated melanomas following treatment with MAPK pathway inhibitors; however, this increase is lost as therapy progresses." (PMID 32260561, 2020). "On the one hand, BRAF mutations were identified in about 80% benign naevi of various histological types, implying a critical role in the initiation of melanoma." (PMID 32083130, 2020). "Among the cellular events that take place during the switch from the proliferative to the invasive phenotype, changes in cadherin expression have been associated with an increment in the invasive capacity of BRAF-mutant melanoma cells." (PMID 33167306, 2020). "Intriguingly, the expression level of the most common oncogene in melanoma, BRAF, was significantly lower in the high-risk group as compared with that in the low-risk group." (PMID 32858528, 2020). "Approximately 50% of melanomas harbor a mutation in the BRAF, mostly confined to a specific point mutation at nucleotide 1799, leading to a change in the V600 amino acid." (PMID 33282420, 2020). "The BRAF V600 is the most commonly found somatic mutation in melanomas and thus has become a potential marker and therapeutic target." (PMID 32188503, 2020). "Regarding gene alterations as well as the upregulation of ABL-1 in BM and downregulation of PIK3CA in metastatic breast cancer cells, BRAF mutations in melanoma and EGFR and KRAS overexpressions in lung cancer have been reported." (PMID 31900168, 2020).
melanoma (continued). "Most reported MAP2K1 mutations have accompanied other driver mutations of melanoma including BRAF, NRAS, and NF1." (PMID 32483240, 2020). "Methods in addition to a BRAF V600E/PTEN-loss melanoma mouse model were used to demonstrate the effect of HI-511 on melanoma development in vitro and in vivo." (PMID 32863956, 2020). "Third, we show that phendione, as a single agent, profoundly diminishes the growth of human melanoma tumors containing BRAF or NRAS mutations." (PMID 32241802, 2020). "Our group has been focusing over the last years on the study of non-genetic mechanisms at the basis of drug resistance to MAPKi in BRAF-mutated melanomas." (PMID 32178301, 2020). "In 2014, a phase 3 trial was carried out that involved 947 patients with unresectable advanced melanoma with a mutation for BRAF V600, V600E or V600K." (PMID 32595510, 2020). "BRAF mutation testing and targeted therapy has yet to be used in melanoma case management in Indonesia." (PMID 32188503, 2020). "We note that a small proportion of cases were pigmented, although our analysis did not reveal tendency towards pigmented epithelioid cytomorphology as noted in previous study of BRAF-mutated melanomas." (PMID 32483240, 2020). "Considering the successful use of BRAF inhibitors in melanoma, we provide a brief overview of the BRAF mutations, including their basic structures and activation mechanisms, and the new classification method for BRAF mutations." (PMID 32476297, 2020). "Tumorigenesis is a result of accumulated multi-gene mutation, in which BRAF gene mutation (mainly BRAF V600E) is significantly higher than other pathogenic genes in melanoma." (PMID 33330635, 2020). "For instance, ∼50% of melanomas harbor recurrent BRAF mutations, which are key to the immune evasion of melanoma and which are amenable to specific treatments, whereas such mutations are much less frequent in colon cancers." (PMID 31990272, 2020). "BRAF mutations occur in 40-50% of melanomas and treatments with specific inhibitors (e.g. vemurafenib, dabrafenib) were reported to be effective in a metastatic disease." (PMID 32194848, 2020). "The effectiveness of the triple combination of dabrafenib, trametinib and pembrolizumab has been investigated in the phase I/II KEYNOTE-022 trial (NCT02130466) that enrolled previously untreated BRAF-mutated advanced melanoma patients." (PMID 33419275, 2020). "Recently, two independent whole-exome sequencing studies revealed a novel gain-of-function mutation of Rac1 in sun-exposed melanomas, being the most frequently observed somatic mutation after BRAF and NRAS mutations." (PMID 32351958, 2020). "Our study demonstrated the detection of resistance mediating BRAF splicing variants in ctRNA of melanoma patients failing BRAF inhibiting therapies." (PMID 33216826, 2020). "Such molecular-targeted therapies are also being developed for cancers with BRAF mutation, a driver of malignant melanoma." (PMID 32206360, 2020). "In early trials, patients with melanomas harboring activating BRAF V600E mutations show high levels of response to BRAF inhibitor (BRAFi) treatment, which makes it a promising therapeutic strategy." (PMID 32413516, 2020). "Globally, 319 advanced melanoma patients undergoing molecular analysis for diagnostic classification of the BRAF/NRAS mutational status were consecutively collected in a hospital-based manner and enrolled into the study." (PMID 32751423, 2020). "For these reasons, we aimed to further characterize the role of BRAF‐V600E mutation in the modulation of PD‐L1, a known immunoregulatory molecule, and galectin‐1 (Gal‐1), a potent immunoregulatory lectin involved in melanoma immune privilege." (PMID 32330348, 2020). "Selective inhibitors of V600E BRAF-mutated melanoma, such as vemurafenib, dabrafenib and encorafenib, prolong survival of patients harboring the V600E mutation." (PMID 33202944, 2020).
melanoma (continued). "The frequency of patients harboring a BRAF mutation (59%) was almost in line with that observed in the general melanoma population." (PMID 33042809, 2020). "BRAF-mutated melanomas are indeed characterized by a young age at diagnosis, absence of chronic sun damage of the skin, and melanoma occurrence on the trunk, which closely reflect the features of our BRAF-mutated patients." (PMID 33003444, 2020). "The BRAF mutation is obviously the most common carcinogenic driver in melanoma, by activating the mitogen-activated protein kinase (MAPK) pathway, which is a pivotal regulator of cellular growth and proliferation." (PMID 33072607, 2020). "We are the first to demonstrate the in vivo efficacy of targeting both MCL1 and BCLXL simultaneously in multiple mouse xenograft studies (both BRAF mutated and BRAF-WT melanoma lines)." (PMID 32513939, 2020). "The meta-analysis presented a correlation to the presence of BRAF gene mutations for patients with melanoma and the populations of Brazil, Australia, Italy, US, and Sweden." (PMID 31274706, 2020). "Most past research on melanoma has mainly focused on genomic variations, among which is the mutated BRAF gene, which is highly related to melanoma." (PMID 32547879, 2020). "In about 50% of melanoma cases (but only in 7–10% of all neoplasms), a mutation in the BRAF gene is present, and 80–90% of these mutations are a missense V600E mutation, where the wild type amino acid 600 (a valine) is replaced by a glutamic acid residue." (PMID 32605090, 2020). "Half of melanoma tumors harbor the V600E mutation in BRAF, which sensitizes these tumors to specific BRAF inhibitors." (PMID 32161259, 2020). "Approximately 60% of melanomas carry an oncogenic BRAF mutation, with BRAFV600E being the most prevalent." (PMID 32455577, 2020). "Melanoma patients carrying a BRAF mutation have been shown to exhibit some short-term benefits from targeted therapies, such as MAPK inhibitors." (PMID 32260561, 2020). "The BRAFV600E mutation is the most common BRAF alteration (80%) and an important oncogenic driver in melanomas, pediatric CNS, lung cancer (3%) and colorectal cancer (6–12%)." (PMID 32878084, 2020). "A meta-analysis including 674 melanoma patients showed an increased risk of mortality in patients with BRAF-mutated melanoma (HR, 2.25; 95% CI, 1.37–2.12) compared with patients with wild-type BRAF melanoma." (PMID 32143442, 2020). "The identification of melanoma driven mutations such as BRAF V600E allowed for a real breakthrough in the treatment of patients with metastatic melanoma." (PMID 32858889, 2020). "BRAF was the most prevalent mutated gene in our cohort (39%, 45/115) and was identified throughout all melanoma site distribution except in uveal melanoma." (PMID 36046072, 2020). "The most commonly reported mutations in cutaneous malignant melanomas are located in BRAF and NRAS genes." (PMID 32637031, 2020). "Strikingly, we observed that IGFBP2 protein levels correlated with resistance to MAPKi in several BRAF-mutant melanoma cell lines and are associated with poor prognosis in primary melanomas." (PMID 32042336, 2020). "More than 30 different mutations have been reported in BRAF, associated with melanoma and other cancers." (PMID 32371878, 2020). "Novel therapeutic strategies relying on the selective inhibition of the MAPK pathway have proven to significantly prolong the survival of patients with advanced BRAF-mutated melanoma." (PMID 32580351, 2020). "Two studies described a total of 31 patients with BRAF-mutated melanoma treated with BRAF-inhibitors (BRAF-i) alone or in combination with mitogen-activated protein kinase inhibitors (MEK-i)." (PMID 32367253, 2020). "In another study, the researchers reported a high concordance between allele-specific TaqMan assay and IHC in BRAF V600E detection analyzing 97 melanomas of 44 multiple primary melanoma patients." (PMID 32695793, 2020).